RETN (resistin)
Diseases named in the same sentence as RETN in open-access papers (continued):
Sharing a sentence is not in itself a finding about the gene and the disease.
cancer (continued). "After excluding one study primarily contributing to between-study heterogeneity, the association between resistin levels and cancer risk was still significant (OR=1.18, 95% CI = 1.09-1.28)." (PMID 27509174, 2016). "Together, these observations suggest that resistin is associated with cancer cell metastasis effect in vivo, but many questions remain to be answered." (PMID 26729407, 2016). "In numerous in vivo studies elevated levels of resistin have been linked to increased incidence risk of many cancers, including breast, endometrial, colorectal, lung, gastric, and esophageal cancers." (PMID 27314854, 2016). "It has also been suggested that the expression of resistin in cancer cells is associated with more malignant clinicopathological processes." (PMID 24555415, 2014). "Recently, resistin has been implicated to serve as a marker of diagnosis and prognosis in different types of cancer." (PMID 24555415, 2014). "Similar data have been reported in mice with cancer cachexia, in which severe weight loss is associated with decreased leptin and insulin, whereas resistin remains unchanged." (PMID 23781298, 2012). "It has been suggested that high resistin levels are related to cancer associated chronic inflammation." (PMID 21254741, 2010). "A meta-analysis was conducted to investigate the association between RETN SNPs and cancer risk." (PMID 40002704, 2025). "Both resistin and leptin can exhibit proliferative, anti-apoptotic, pro-inflammatory effects and stimulate angiogenesis, making them potential diagnostic and prognostic biomarkers for cancer." (PMID 37238197, 2023). "Resistin expression was associated with pathological grade (P = 0.017) and LN metastasis (P = 0.045) but not with age, histotype, residual tumor after initial laparotomy, serum cancer antigen 125, and FIGO stage." (PMID 34659568, 2021). "Emerging evidence indicates that resistin and fascin-1 may possess a causal role in the development of several types of cancers." (PMID 32420377, 2020). "Our observed increased risk of cancer mortality associated with higher serum resistin levels among Blacks suggests that if validated in larger cohorts, clinical strategies focused on resistin control may be a promising cancer prevention strategy." (PMID 29662629, 2018). "We identified 42 potentially relevant papers concerning resistin in relation to cancer risk." (PMID 27509174, 2016). "The association of resistin with cancer progression is less investigated and understood." (PMID 24465803, 2014). "It has been recently suggested that adipocytokines, such as TNF–alpha, IL–6, type–1 plasminogen activator inhibitor (PAI–1), adiponectin, leptin, resistin, visfatin and apelin are associated with the risk of cancer at various sites (e.g., breast, prostate gland, endometrium and colorectum)." (PMID 21254741, 2010). "Similarly, we observed that all tested CRC cells converted adipocytes into cancer-associated adipocytes, which decreased lipid content and the expression of genes that are characteristic of adipocytes (including PPARγ, resistin, adiponectin, FABP4, perilipin, and LIPE)." (PMID 37316878, 2023). "Thus, resistin emerges as an important marker implicated in the development of cancer." (PMID 36428592, 2022). "Moreover, our results suggest that high serum resistin levels are related to cancer-associated chronic inflammation and support the previous study in which resistin exhibited pro-inflammatory properties by up-regulating the expression of TNF-α and IL-6 and the activation of monocytes." (PMID 26690142, 2015). "Moreover resistin is linked with many chronic inflammatory conditions, including cancers." (PMID 24551805, 2013). "Given its capacity to modulate the production of immune molecules and its indirect regulatory effects on the MAPK pathway, resistin has been the subject of investigation in various human cancers." (PMID 40620232, 2025).
cancer (continued). "It was also reported that higher serum levels of the pro-inflammatory cytokine resistin in cancer patients promoted the stemness of BCa cells." (PMID 39040042, 2024). "TNFα, which is also promoted by resistin, is involved in angiogenesis, metastasis, growth, and differentiation of cancer." (PMID 39184804, 2024). "The role of resistin in cancer spread is facilitated by promoting cell adhesion molecules that help in cell translocation, a crucial step in metastasis." (PMID 39184804, 2024). "The research results indicated that resistin and visfatin levels had significantly decreased after cancer treatment." (PMID 39184804, 2024). "Cancer cachexia also reduced the expression levels of adiponectin, aP2, and resistin, but BSN restored its expression levels." (PMID 38807976, 2024). "One way that resistin contributes to cancer is through inflammatory pathways since resistin is highly expressed in immune cells that infiltrate adipose tissue, and its levels are an indicator of a person's inflammatory status." (PMID 39184804, 2024). "Elevated resistin in BCa promotes the invasion and metastasis of cancer cells by inducing phosphorylation of c-Src, PP2A, PKCα, ezrin, radixin, and moesin." (PMID 39040042, 2024). "Research by Yanran Li and colleagues has shown that human RETN acts as a pro‐inflammatory molecule, impacting a variety of chronic inflammatory diseases, metabolic disorders, and cancers, which highlights its potential role in inflammatory pathways." (PMID 39664590, 2024). "In cancer cells, resistin promotes phosphorylation of Src (a downstream target of FAK kinase) and increases intracellular calcium levels." (PMID 38137922, 2023). "Adipokines are fat-derived factors and include leptin, adiponectin, resistin, and visfatin for which a role in cancer cachexia has been suggested." (PMID 35406586, 2022). "A variety of mechanisms have been proposed to mediate the link between metabolism and cancer, including leptin, adiponectin, resistin, inflammatory cytokines, reactive oxygen species, sex hormones, and others." (PMID 35595952, 2022). "Preclinical and clinical studies have reported high serum resistin levels in patients with various types of cancer, generating an increased mortality rate compared to patients expressing low resistin levels." (PMID 36291097, 2022). "Inflammatory cytokines, such as adiponectin, resistin and leptin, have been shown to correlate with the development, progression and mortality of various types of cancer." (PMID 36497484, 2022). "In conclusion, resistin is closely related to tumorigenesis and tumor development, and its cancer-promoting effect is mainly manifested in the induction of epithelial mesenchymal transition." (PMID 34485124, 2021). "The resistin treatment enhanced stemness in cancer cells by upregulating the stemness markers aldehyde dehydrogenase-1 (ALDH1), CD44, Oct4, Nanong and Sox2 and downregulating CD44 cell surface expression." (PMID 34588926, 2021). "Mechanistically, resistin was found to promote invasion, migration and cellular protrusions in cancer cells by inducing the reorganization of F-actin filaments." (PMID 34588926, 2021). "The positive correlation between serum resistin levels, cachexia and metastasis in gastroesophageal cancers affirms its direct involvement in cancer pathogenesis." (PMID 34588926, 2021). "The adipokine resistin participates in several physiologic and pathologic processes throughout the body, including metabolism, inflammation, autoimmunity, and various cancers, including CRC." (PMID 32420377, 2020). "The aim of the study was to establish the correlation between the level of the adipokines—adiponectin, resistin, apelin—and cancer cachexia." (PMID 32660156, 2020). "Adipocytes attenuated Doxorubicin-induced apoptosis in cancer cells by increasing the protein expression of anti-apoptotic marker blc-2 as well as increasing the synthesis of resistin." (PMID 32257945, 2020).
cancer (continued). "Elevated expression of leptin and resistin was found to regulate the response of cancer cells to chemotherapy." (PMID 32489325, 2020). "•Suppressor of cytokine signaling 3 (SOCS3) can be used as a control gene to evaluate the responsiveness of cancer cells to resistin treatment." (PMID 31417946, 2019). "It has been shown that leptin and resistin stimulate the Akt signaling in cancer cells, and hyperactivated Akt pathway was associated with increased protein levels of FASN and Cav-1." (PMID 29568521, 2018). "Concurrently, protein expression levels of VCAM-1, ICAM-1, resistin, biomarkers in plasmas are clearly up regulated during initial stage of cancer, but significantly down regulated in later stages of cancer in patients." (PMID 29606130, 2018). "In disease conditions, such as cancer, the levels of resistin can be much elevated, correlating with the tumor stage." (PMID 30131543, 2018). "Many studies showed resistin levels were similar, even lower in cancer patients compare with normal controls." (PMID 27509174, 2016). "Mice that received anti-resistin antibodies showed decreased incidence of cancer development and metastasis." (PMID 26729407, 2016). "Except for the studies identified as major contributors to heterogeneity by Galbraith plot, resistin levels were still higher in cancer patients (SMD = 0.75, 95% CI = 0.63-0.87) in retrospective studies." (PMID 27509174, 2016). "After excluding those studies, high resistin levels were still found in cancer patients (SMD = 0.75, 95% CI = 0.63-0.87, I2 = 39.3%, P (for heterogeneity analysis) = 0.087)." (PMID 27509174, 2016). "For this, we studied the effect of resistin on motility and invasiveness, which are two important characteristics of the aggressive cancer cells." (PMID 25868978, 2015). "The upregulation of resistin in these cancers therefore promotes a vicious cycle of synthesis and release of inflammatory cytokines further promoting tumor cell progression." (PMID 26097512, 2015). "Lately, implications for resistin as a biomarker in cancer and potential area for therapeutic intervention have been drawn." (PMID 26097512, 2015). "MiRNAs have been reported as an important regulator in cancer progression and metastasis, and our results indicate that resistin promotes cell migration by up-regulation of MMP-2 expression." (PMID 25404641, 2015). "Other published studies have also reported a role of resistin in cancer progression, invasion and metastasis." (PMID 25868978, 2015). "Because cell adhesion molecules have been shown to be critical in cancer cell metastasis, we examined the effect of resistin on the ICAM-1 and VCAM-1 mRNA and cell surface protein expressions in SK-Hep1 cells." (PMID 24555415, 2014). "An increasing number of studies have focused on the role of resistin in cancer development, and the impact of resistin on inflammation is the focus of several current academic studies." (PMID 24929539, 2014). "The importance of resistin in cancer cachexia appears to be different from this, which was proposed for leptin in our previous study." (PMID 25049439, 2014). "Immunohistochemistry analysis has shown a heterogeneous and diffuse weak pattern of resistin expression in cancer tissues." (PMID 24551805, 2013). "A previous study has compared resistin protein expression in cancers with paired normal tissue using ELISA and western blot methods and reported an upregulation of resistin in CRC tissues." (PMID 24551805, 2013). "Suggestions about the prognostic value of adiponectin and resistin in the assessment of severity and outcome of inflammatory diseases and cancer appeared in several recent publications." (PMID 24259947, 2013). "Further studies found resistin being significantly elevated in cancer patients and in several studies stage progression significantly correlates with resistin concentrations." (PMID 23173608, 2012).
cancer (continued). "Meta-analysis results further confirmed the absence of a significant association between RETN polymorphisms and cancer risk." (PMID 40002704, 2025). "However, studies exploring the relationship between resistin and cancer cachexia remain limited at this time." (PMID 39764565, 2025). "In addition to alterations in adiponectin and leptin levels, elevated levels of other adipokines, such as resistin, interleukin‐6 (IL‐6), and tumor necrosis factor‐alpha (TNF‐α), are associated with an increased risk of cancer." (PMID 40620232, 2025). "However, there is evidence for the implication of other adipokines such as resistin, visfatin, apelin and chemerin in the development of cancer." (PMID 37686525, 2023). "Furthermore, resistin has been proposed as a biological marker due to its relationships to chronic diseases, such as cardiovascular diseases and cancers." (PMID 38140309, 2023). "Although some previous studies and meta-analyses have reported a positive correlation between increased resistin levels and cancer, another meta-analysis did not confirm a relationship between resistin and cancer risk." (PMID 37048738, 2023). "Signaling pathways connecting resistin with cancer include those related to TLR4, PI-3K, and NFκβ." (PMID 35453670, 2022). "Only one study has evaluated the effect of resistin on autophagy in cancer cells." (PMID 36291097, 2022). "This tissue secretes adipocytokines such as visfatin, resistin, and leptin, which may be helpful in the prognosis and diagnosis of cancer, which can be beneficial for cancer prognosis and diagnosis." (PMID 36415563, 2022). "Since we used triple-negative BC cell lines in our study, resistin-mediated downregulation of Let-7a may represent another mode through which Let-7a can be regulated in cancer cells." (PMID 34572725, 2021). "In humans, resistin is considered to be a pro-inflammatory molecule expressed in immune cells, which plays a regulatory role in many chronic inflammatory diseases, metabolic diseases, infectious diseases, and cancers." (PMID 34220862, 2021). "In this regard, studies from several research groups have indicated that resistin can support cancer growth and metastasis through Stat3 activation and by triggering the ezrin/radixin/moesin (ERM) protein family, which plays an essential role in cell migration and invasion." (PMID 34681797, 2021). "Here we investigated some RETN SNPs with higher impact or risks in various cancers." (PMID 32226495, 2020). "Later on, a connection between resistin and human cancers was sought." (PMID 30131543, 2018). "Here, we examine the association between four single nucleotide polymorphisms (SNPs) of the RETN gene (rs3745367, rs7408174, rs1862513, and rs3219175) and OSCC susceptibility as well as clinical outcomes in 935 patients with OSCC and in 1200 cancer-free healthy controls." (PMID 30406149, 2018). "There is a considerable amount of experimental and epidemiological evidences which suggest that resistin may have pathophysiological effects, particularly in some cancer types, in addition to its traditional roles in energy homeostasis." (PMID 29568521, 2018). "Another important adipokine, resistin, is known to promote cancer growth." (PMID 29568521, 2018). "Higher resistin levels were present in cancer patients (SMD = 0.94, 95% CI = 0.63-1.25)." (PMID 27509174, 2016). "The result of 18 studies of pooling measures on SMD analysis was that high resistin levels were associated with increased cancer risk (SMD = 0.94, 95% CI = 0.63-1.25), but not in the pooling SMD analysis of prospective studies." (PMID 27509174, 2016). "High resistin levels were found in cancer patients (OR= 1.20, 95% CI= 1.10-1.30)." (PMID 27509174, 2016). "Studies revealed resistin could promote the proliferation, angiogenesis, and metastasis of cancer cells by stimulating specific signaling pathways including p38 MAPK/NF-kB and PI3K/Akt." (PMID 27509174, 2016).
cancer (continued). "However, for retrospective studies, stratification analysis showed that resistin levels were always higher in cancer patients." (PMID 27509174, 2016). "Although the studies have some discrepancies, the circulating levels of serum resistin may serve as biomarkers for the pathogenesis and progression of many cancers, in particular CRC." (PMID 26690142, 2015). "Despite the many studies focusing on resistin in metabolic disorders and cancer, its function during infection is currently unknown." (PMID 25568944, 2015). "Similarly, human resistin expression is induced in a variety of inflammatory settings including endotoxemia, metabolic disorders and cancer." (PMID 25568944, 2015). "Contrary to resistin is the role of the resistin-like molecule RELMβ in carcinomas." (PMID 26097512, 2015). "Serum resistin was significantly higher in cancer patients than in the controls." (PMID 25049439, 2014). "The aim of the present study was the investigation of (a) possible relationship between cancer cachexia and levels of serum adiponectin, apelin, and resistin and (b) correlation of serum adipocytokines with clinical, pathological, and blood parameters of cancer patients." (PMID 25049439, 2014). "On the other hand, the association between resistin plasma level, independent from BMI, and CRP (C - reactive protein) as an inflammatory phase protein factor in inflammatory related disorders including cancers especially CRC has been widely reported." (PMID 24551805, 2013). "Finally, RETN is a member of the cysteine-rich proteins family secreted from adipocytes and monocytes in humans and may play a role in modulating cancer pathogenesis." (PMID 36624406, 2023). "Although individuals who reported prevalent cancers at baseline were excluded from our analysis, we speculate whether some individuals may have had undiagnosed cancer at baseline, which may have led to higher resistin concentrations in these individuals." (PMID 36428592, 2022). "In contrast to its production by adipocytes in mice, human resistin is expressed predominantly in leukocytes, and has always been considered as a pro-inflammatory molecule that plays a regulatory role in many human chronic inflammatory diseases, metabolic diseases, infectious diseases, and cancers." (PMID 34220862, 2021). "This review reported the findings of adipokines (leptin, adiponectin, resistin, apelin, and visfatin) in cancer cachexia, highlighting that to study in-depth the involvement of these hormones in this pathology could lead to the development of new therapeutic strategies." (PMID 32660156, 2020). "However, the studies concerning resistin and cancer cachexia are limited at this moment." (PMID 32660156, 2020). "Thus, through multiple mechanisms, resistin can induce angiogenesis in different cancers." (PMID 30131543, 2018). "Whether circulating resistin levels are higher in cancer patients is inconsistent." (PMID 27509174, 2016). "Moreover, resistin increased expression of vimentin, a key molecule for cancer cell invasion." (PMID 26729407, 2016). "However, the precise roles of resistin on cancer development are still unclear." (PMID 24555415, 2014). "The role of resistin in CRC is not fully understood, but several mechanisms have been proposed to understand its involvement in cancer." (PMID 39184804, 2024). "In this work, we show that treatment with resistin induces an increase in FAK phosphorylation levels and an increase in MMP-2 and MMP-9 secretion in PC3 cancer cells." (PMID 38137922, 2023). "Similar to the potential cross-talk between mesothelial cells and cancer cells, we identified possible interactions between LA-TAMs/mesothelial cells by SPP1, RETN, LGALS9, NAMPT, and HBEGF secretion." (PMID 37649596, 2023). "Another pro-inflammatory adipokine, visfatin, like resistin, induces EMT in cancer and promotes the proliferation of different types of tumor cells." (PMID 37686525, 2023).